SCARNA12 (small Cajal body-specific RNA 12)
Synonyms: U89
Gene: Small nucleolar RNA gene on chromosome 12 (6,967,337 to 6,967,606, reverse strand). Ensembl gene ENSG00000238795.
Gene Ontology:
Biological process: RNA processing
Cellular component: nucleolus
Homologues: Orthologues: chimpanzee SCARNA12 (99% identical), macaque SCARNA12 (96% identical), pig SCARNA12 (78% identical), rabbit SCARNA12 (76% identical), guinea pig SCARNA12 (73% identical), mouse Gm23547 (71% identical), rat LOC120102747 (70% identical).
Diseases named in the same sentence as SCARNA12 in open-access papers:
SCARNA12 is named in the same sentence as 3 diseases in open-access papers, as found by Europe PMC text mining. Sharing a sentence is not in itself a finding about the gene and the disease. The quoted sentences say what the papers report.
bladder cancer (1 paper, 2024). "To further investigate the mechanism by which SCARNA12 regulates gene expression in bladder cancer cells, we utilized ChIRP to identify proteins interacting with SCARNA12." (PMID 38339238, 2024). "Therefore, we hypothesize that SCARNA12 may interact with the transcription factor H2AFZ, and this interaction could potentially impact the expression of ECM genes in bladder cancer cells, thus contributing to the development of bladder cancer." (PMID 38339238, 2024).
cancer (1 paper, 2023). A tumor composed of atypical neoplastic, often pleomorphic cells that invade other tissues. "In summary, this study confirms that SCARNA12 is upregulated in various cancers, including CRC." (PMID 37907779, 2023).
tumor (1 paper, 2024). "Furthermore, SCARNA12 knockdown could suppress the in vivo tumor growth in nude mice." (PMID 38339238, 2024). "Additionally, in situ hybridization (ISH) experiments confirmed positive expression of SCARNA12 in BLCA tissues, with localization observed in both the cytoplasm and nucleus, and the ISH score of SCARNA12 in tumor tissue was notably higher than that in adjacent tissue." (PMID 38339238, 2024).